KIT (KIT proto-oncogene, receptor tyrosine kinase)
Diseases named in the same sentence as KIT in open-access papers (continued):
Sharing a sentence is not in itself a finding about the gene and the disease.
seminoma (continued). "We postulate that only seminomas without KIT mutations may be capable of acquiring nonseminomatous histology because all NSGCTs, including mixed TGCTs with seminoma components, lacked KIT mutations." (PMID 29898407, 2018). "The low co-expression of c-KIT and PLAP in SEM could result from the different cellular origin of seminomas, because c-KIT is expressed in both spermatogonia and prespermatogonia whereas PLAP is expressed only in prespermatogonia, while in people both cells give rise to CSEM." (PMID 25096628, 2014). "A striking difference between area 1 and area 2 of the seminoma tumour specimen was the higher levels of transcription factor LHX1 and the tyrosine kinase receptor KIT in area 1 ROIs." (PMID 40693358, 2026). "The pattern of alterations observed suggests involvement of the KIT/RAS/MAPK and PI3K/AKT/mTOR (PAM) signaling pathways in seminoma development." (PMID 41154418, 2025). "These suggest involvement within the KIT/RAS/MAPK and PI3K/AKT/mTOR (PAM) pathways for seminoma development." (PMID 41154418, 2025). "Typical markers for seminoma include positive placental alkaline phosphatase (PLAP), OCT3/4, and c-KIT (CD117)." (PMID 39463534, 2024). "The DPPA3 and XIST genes were hypermethylated in LT-PTCs as compared to d0-PTCs and seminomas, MGMT displayed a variable DNA methylation pattern between and within groups and the KIT promoter was stably hypomethylated in all groups including seminomas." (PMID 32176716, 2020). "KIT mutant seminomas had lower-level copy number levels and gene expression of KRAS than either KIT WT seminomas or NSGCTs." (PMID 29898407, 2018). "Three of these studies classified seminomas in the dog as classical (SE) and spermatocytic (SS) seminoma by means of morphological evaluation, PAS reaction and PLAP and c-KIT expression." (PMID 22986090, 2012). "One of the two sections with PAS and PLAP positive, intratubular seminoma showed strong membranous and cytoplasmic c-KIT staining in the same cells, while the other showed only scattered tumour cells with cytoplasmic c-KIT staining." (PMID 22986090, 2012). "Immunohistochemical analysis for PLAP, c-KIT, DAZ and DMRT-1 expression was performed and the authors concluded that the investigated canine seminomas closely resembled SS." (PMID 22986090, 2012). "While seminoma-specific data is scarce, studies have shown the PAM pathway as a progression driver for malignant proliferation through various mechanisms of activation, despite activation by KIT in part." (PMID 41154418, 2025). "Based on the finding that the KIT gene is mutated in some seminomas but appears to be wild type in non-seminomas, it has been proposed that only seminoma cells with wild type KIT can transform into non-seminoma." (PMID 37048077, 2023). "Histological confirmation of seminoma was established following a CT-guided biopsy of the retroperitoneal mass, with immunohistochemistry positivity for CD117 (c-KIT) and Oct 3/4, and negative for cytokeratin AE1/AE3, S100 protein, CD45, desmin, and CD56." (PMID 31142361, 2019). "Several genomewide studies suggested driver mutations in only three genes (KIT, KRAS, and NRAS) in 4–31% of seminoma, and up to 14% of non-seminoma patients." (PMID 30547014, 2018). "Most importantly keratin stains are negative, excluding embryonal carcinoma, and placental alkaline phosphatase and KIT (CD117) are also negative, excluding seminoma." (PMID 23762714, 2013). "Although ovarian dysgerminomas resemble seminomas in morphology and chromosomal aberrations, expression of c-KIT is not extensively explored." (PMID 22937135, 2012). "However, this concept was recently challenged by three publications in which canine seminomas were characterised morphologically and by immunohistochemical analysis for PLAP and c-KIT." (PMID 22986090, 2012). "However, in patients SP4 and SP5, both KIT and KRAS mutations occurred in the right but not in the left synchronous seminomas." (PMID 40358182, 2025).
seminoma (continued). "Notably, ecDNA contributed to amplification of oncogenes including KRAS (5 seminomas), KIT (1 seminoma), and MDM2 (1 seminoma, 2 non-seminomas)." (PMID 40568177, 2025). "KIT and KRAS mutations are reported more frequently in seminomas when compared with non-seminomas." (PMID 37007070, 2023). "The initial speculation regarding the presence of KIT mutations in IGCTs arose from the observation that almost all testicular seminomas/non-seminomas exhibit KIT membrane staining, with a considerable portion harboring c-kit mutations." (PMID 38012690, 2023). "Notably CN-Sig-6, which reflects high copy number states from focal amplification, was particularly high in seminomas with (i) increased 12p copy number, (ii) KRAS copy number and/or, (iii) KRAS mRNA expression (without KIT/KRAS/NRAS mutations)." (PMID 32366847, 2020). "The tissue specific adult stem cell-related factors AP-2γ and KIT are highly expressed in immature gonocytes, testicular carcinoma in situ (the pre-invasive stage of testicular GCTs) and in seminomas, and AP-2γ, but not KIT, is expressed in embryonal carcinoma." (PMID 17274819, 2007). "Because KIT mutation was never observed in tumors lacking seminoma components, we postulate that this subset of seminomas is locked in a PGC-like status and remain pure seminomas, while those lacking KIT mutations may have the potential to differentiate into other histologies." (PMID 29898407, 2018). "Although Tcam-2 cells are not identical to seminomas in vivo, solid analogies exist regarding the expression of stem cells markers such as OCT4, NANOG, PLAP, KIT, and D2-40." (PMID 35269507, 2022). "It is important to mention that the c-KIT positive non-GIST tumors, such as small or large cell carcinomas, renal chromophobe cell carcinomas, thymic carcinomas or seminomas, did not display PKCθ positivity." (PMID 28915565, 2017). "Finally, currently there are no standardised criteria regarding interpretation of PLAP-, c-KIT- and PAS-sections of canine seminomas." (PMID 22986090, 2012).
lung cancer (86 papers, 2004 to 2025). A malignant neoplasm involving the lung. "Simultaneously, samples from a brain metastasis of breast and lung cancer patients had more KIT gene mutations than samples from the primary tumor." (PMID 35681762, 2022). "For instance, exosomes of this type promoted the growth of lung adenocarcinoma cells by transferring KIT (a member of the tyrosine kinase family of growth receptors) to cancer cells, where KIT positivity was associated with short-term lung cancer survival." (PMID 36119094, 2022). "Three patients were treated with imatinib, erlotinib, and vemurafenib on the basis of an Asp572Gly KIT mutation (lung cancer), an EGFR amplification (cervical cancer), and a Val600Glu BRAF mutation (colorectal cancer), respectively." (PMID 32914004, 2018). "This speculation is further supported by our previous research demonstrating that when KIT or PTEN cancer-critical genes are mutated in lung cancer, galectin-1 levels are elevated." (PMID 38539500, 2024). "Several studies have indicated that KIT is associated with the development of lung cancer." (PMID 38180107, 2023). "Dasatinib, a multi-kinase inhibitor targeting BCR-ABL, SRC, and c-KIT, has been shown not only to inhibit the growth of lung cancer-derived CAFs but also to revert their oncogenic phenotype to that of non-tumorigenic fibroblasts." (PMID 41614761, 2025). "For this purpose, we chose several common markers associated with lung cancer CSCs: aldehyde dehydrogenase (ALDH), CD44, Octamer-binding transcription factor 4 (Oct4), KIT proto-oncogene, receptor tyrosine kinase (c-Kit), and Nestin." (PMID 37233697, 2023). "It has been reported that Bim was critical for erlotinib-induced apoptosis in EGFR mutant lung cancer cells and imatinib-induced apoptosis in KIT dependent GIST cells." (PMID 24009732, 2013). "The fact that KIT activation induces proliferation or invasion in vitro was also reported in lung cancer and colorectal cancer." (PMID 17044945, 2006). "Although no specific targeted drugs have been approved for lung cancer, drugs such as cabozantinib, axitinib or regorafenib have been approved for other tumors harboring KIT mutations." (PMID 33153192, 2020). "Exosomes derived from lung cancer cells possess SCF for binding to mast cells via KIT." (PMID 31664930, 2019). "Several markers, including ALDH, ATP binding cassette subfamily G member 2 (ABCG2), CD44, CD117/KIT, CD133, and stem markers Nanog and OCT3/4, are overexpressed in lung cancer and have been used to identify CSC populations." (PMID 37468874, 2023). "In vivo generated afatinib-resistant clones of H1975 lung cancer cells showed decreased expression of EGFR, HER2, HER3 and HER4 and increased expression of MET, c-KIT and PDGFRβ." (PMID 31557260, 2019). "Mast cell-derived KIT acts as a functional protein that interacts with tumor cells via exosomes and subsequently activates KIT-SCF signal pathway, which accelerates the proliferation in lung cancer cells." (PMID 31664930, 2019). "The proapoptotic BH3-only protein Bim was essential for imatinib-induced apoptosis in KIT-dependent gastrointestinal stromal tumor cells and erlotinib-induced apoptosis in EGFR mutant lung cancer cells." (PMID 25431951, 2014). "Class III receptor tyrosine kinase (RTK) inhibitors targeting mainly FLT3 or c-KIT have not been well studied in lung cancer." (PMID 31554189, 2019). "In other two phase II clinical trials in lung cancer and uterine carcinosarcomas, the high expression of KIT did not correlate with response to imatinib." (PMID 23497641, 2013).
lung cancer (continued). "Currently, genetic testing of KIT and PDGFRA is essential before treatment initiation, and comprehensive genomic profiling, such as for lung cancer, should be considered to identify driver mutations (e.g., SDH, BRAF, NF1, NTRK fusion, and FGFR fusion) for GISTs without KIT and PDGFRA mutations." (PMID 35965531, 2022). "Interestingly, some incoming signaling pathways were found to be specific to one subtype of lung cancer, as exemplified by HGF (a new highlight in the treatments of lung cancer), KIT (activating the JAK/STAT and PLC/PKC signaling pathways) in LUAD, and the CSF3 and CDH5 in LUSC." (PMID 36008393, 2022). "Oncogenic KIT shuttled in EVs may impact the pathogenesis of diseases, or reflect disease status as implied in studies of EGFR‐containing EVs in lung cancer or other malignancies." (PMID 36239715, 2022). "We next analyzed the protein expression of oncogenes known to be transcriptionally upregulated in tuft cell-like lung cancer subsets, i.e., BCL2, MYC, and KIT, because their expression might further delineate tuft cell-like variants and open new therapeutic perspectives." (PMID 36402755, 2022). "Furthermore, TKIs increase PM localization of EGFR in lung cancers and PDGFRA/KIT in GISTs." (PMID 31484543, 2019). "Murine lung cancer cells lacking the Mir181ab1 cluster were more sensitive to the multiple–tyrosine kinase (BCR-ABL, SRC, c-KIT) inhibitor dasatinib than those cells in which Mir181ab1 was reconstituted." (PMID 31874105, 2020). "Also, all the tuft cell-like lung cancer subtypes significantly expressed BCL2 and KIT, and tuft cell-like NECs unlike non-tuft cell-like NECs overexpressed MYC." (PMID 36402755, 2022).
mucosal melanoma (75 papers, 2008 to 2025). A melanoma that arises from a mucosal site. "In one meta-analysis, KIT mutations were significantly associated with mucosal melanoma in white patients and acral melanoma in Asian patients." (PMID 41301010, 2025). "Mucosal melanoma also frequently exhibits mutations in genes such as v-kit Hardy-Zuckerman 4 feline sarcoma viral oncogene homolog (KIT), neurofibromatosis (NF), and spliceosome factor 3b (SF3B1), with KIT specifically associated with vulvar melanoma." (PMID 39006602, 2024). "Activating mutations in c-KIT are frequently found in mucosal melanoma, and this immunotherapy has emerged as a potential treatment." (PMID 35893303, 2022). "This mutation is within the protein kinase domain of the KIT protein and has been identified before in a metastatic non-small-cell lung cancer and a vocal cord mucosal melanoma, but to our knowledge, this is the first time encountering this mutation in a GIST." (PMID 35804982, 2022). "A case report describes a patient with stage IV M1b metastatic and mucosal melanoma with a KIT mutation who attained a complete response with combination therapy consisting of sorafenib, temozolomide, wide local excision, and radiation." (PMID 35954441, 2022). "All 4 cases of KIT amplifications were found in mucosal melanoma, among which 1 case was co-occurred with p.W557G mutation." (PMID 35688842, 2022). "Conversely, when factoring in putative approved off-label allocations, 16.3% of patients harboured a candidate target including 10.2% of mucosal melanoma cases containing KIT mutations, which confer sensitivity to imatinib." (PMID 35849877, 2022). "CTNNB1 mutations are more common in nevi-derived CMs, suggesting a pivotal role of the Wnt pathway in their tumorigenesis, whereas the presence of KIT/SF3B1 mutations suggests a mucosal-specific tumorigenic pathway as for other mucosal melanomas." (PMID 34830847, 2021). "On the other hand, activating mutations in KIT are relatively common in mucosal melanoma, being found in approximately 40% of all patients." (PMID 34149718, 2021). "These mutations have been observed previously in mucosal melanoma, particularly KIT and SF3B1 mutations." (PMID 33724703, 2021). "KIT aberration (mutation) was present in 11% of the tested population and again very low incidence in mucosal melanoma (4 out of 34 tested)." (PMID 35211204, 2021). "For example, a patient with anal mucosal melanomas and a KIT mutation (Val560Asp) in exon 11 had a complete response to sorafenib with temozolomide that lasted 5 months." (PMID 34831002, 2021). "KIT gene mutations are present in 39% of mucosal melanomas (MM), 36% of acral lentiginous melanomas (ALM), and in 28% of skin with chronic solar damage." (PMID 31274706, 2020). "Although typically of short duration, antitumor activity with KIT inhibitors like imatinib has been observed in mucosal melanoma harboring KIT mutations." (PMID 31262050, 2019). "Driver mutations in GNAQ and GNA11 were identified in two uveal melanomas, and a driver mutation in KIT was found in mucosal melanoma." (PMID 29991680, 2018). "The identification of activating mutations in the KIT gene in patients with mucosal melanoma is important to improve knowledge of tumor biology and the design of clinical research protocols with imatinib." (PMID 29796159, 2018). "Activating mutations in the c-KIT gene are detected in a significant number of patients with mucosal melanoma." (PMID 26420268, 2015). "Tumors harboring KIT mutations, commonly seen in acral lentiginous and mucosal melanomas, may benefit from tyrosine kinase inhibitors like imatinib, although treatment resistance is frequently observed." (PMID 40984902, 2025). "Both acral and mucosal melanomas have KIT mutations in approximately 15% of cases." (PMID 35893303, 2022).
mucosal melanoma (continued). "In a phase II trial evaluating the efficacy of imatinib in patients with metastatic melanoma [17/24 (71%) patients with mucosal melanoma] harboring activating KIT mutations or amplifications, imatinib provided an overall response rate of 29% and an overall disease control rate of 50%." (PMID 34149718, 2021). "Moreover, in mucosal melanoma a distinct model of chromosomal aberrations has been reported, as well as a higher rate of copy number alterations, and frequent KIT mutations in urogenital melanomas." (PMID 34503234, 2021). "Mutations of the KIT gene were correlated to mucosal melanoma (odds ratio = 1.59)." (PMID 31274706, 2020). "Molecular epidemiology studies indicated that the mutation pattern of mucosal melanoma is fundamentally different as compared to cutaneous locasion since KIT is the most frequently involved oncogene (15–25%) followed by a much less frequent involvement of BRAF, NRAS (<10%)." (PMID 31848942, 2020). "Though ATRX and KIT mutations may also occur in mucosal melanomas, CM is generally thought to exhibit a different genetic profile that more closely resembles cutaneous melanoma than mucosal melanoma." (PMID 40552248, 2025). "However, it may be pointed out that the number of acral and mucosal melanoma which are generally associated with a high frequency of KIT mutations, was low in our dataset." (PMID 33648909, 2021). "Other genomic mutations that have been identified include alterations in NRAS (∼28% of cases), NF1 (∼14% of cases), and KIT (∼15%–20% of cases of acral or mucosal melanoma)." (PMID 39542696, 2024). "The two KIT-mutated cases carried SF3B1 mutations and were located on sun-protected mucosa, a genotype shared with genital and anorectal mucosal melanomas." (PMID 34359736, 2021). "The efficacy and safety of targeted therapies, especially of agents targeting c-KIT, have also been investigated in patients with mucosal melanoma." (PMID 34149718, 2021). "In our cohort, 185 patients with metastatic disease had predominantly mucosal melanoma, 20% had BRAF mutation, 11% KIT mutation and only one-third took any systemic treatment with a median PFS of 9 months, and one-third of them took an ICI agent." (PMID 35211204, 2021). "The driver mutations in the genes RICTOR, CDK4, PDGFRA, KIT were specific for acral melanoma, while the amplification or deletion of the genes CCND2 and CHEK2 are uniquely found in mucosal melanoma." (PMID 32825510, 2020). "In acral and mucosal melanomas, KIT has been considered to be one of the reasonable therapeutic targets." (PMID 30675668, 2019). "A patient with a KIT L576P vaginal mucosal melanoma and extensive metastases to lymph nodes demonstrated a dramatic reduction in metabolic activity with Sprycel." (PMID 21479172, 2011). "Major driver mutations in mucosal melanoma were detected in NRAS, KRAS, NF1, PTEN, GNAQ, and KIT." (PMID 39564955, 2024). "It should be noted we excluded acral lentiginous and mucosal melanoma, thus there were no c-KIT mutations identified." (PMID 37444637, 2023). "In addition, co-mutations of KIT and NF1 have been reported in mucosal melanoma, although they are rare." (PMID 34102999, 2021). "Our data suggest that mutant KIT/SF3B1 co-occurrence may be a specific feature of a subset of mucosal melanomas including ConjMel, anorectal, and genitourinary melanomas." (PMID 34359736, 2021). "The mutations of the KIT gene are found with greater frequency for mucosal melanoma (30%), unlike for BRAF and NRAS genes." (PMID 31274706, 2020). "Mutations in KIT, which are commonly found in acral melanoma and mucosal melanoma of other localizations, were not present in our cohort of sinonasal melanoma." (PMID 31500314, 2019). "Many variants have been described in the context of mucosal melanoma, but besides KIT mutations, there is still no clear consensus on the most frequent driver mutations." (PMID 31398831, 2019).